LEP (leptin)
Diseases named in the same sentence as LEP in open-access papers (continued):
Sharing a sentence is not in itself a finding about the gene and the disease.
atherosclerosis (continued). "Leptin, together with adiponectin, is a link in the adipovascular axis, connecting the excessive fat tissue with inflammation and atherosclerosis, and all the pathologies that derive from their imbalance." (PMID 30405857, 2018). "We found that puerarin (with the highest content in the EEDL) is the main component to attenuate atherosclerosis by regulating leptin and the LDL receptor." (PMID 29896109, 2018). "Changes in leptin expression were strongly and positively correlated with adipose ALA levels and inversely correlated with risk of atherosclerosis." (PMID 29631590, 2018). "Results from various studies that examine the effect of leptin on atherosclerosis are contradictory." (PMID 28950870, 2017). "CIMT is a well-known marker of subclinical atherosclerosis and its measurement is a noninvasive and inexpensive method of detecting subclinical atherosclerosis; it is in relationship to adiponectin, leptin and hsCRP." (PMID 27598978, 2017). "There is increasing experimental evidence that leptin and the leptin receptor have specific effects on the development of atherosclerosis." (PMID 28030540, 2016). "The mechanism through which insulin promotes atherosclerosis also involves epigenetic modifications; high insulin levels reduce methylation of the leptin and adiponectin promoters, which contributes to atherosclerosis." (PMID 27832775, 2016). "Little is known about the relationship between LTPA, subclinical atherosclerosis and biomarkers involved in regulating energy balance, like leptin or irisin." (PMID 27044376, 2016). "The involvement of leptin in promoting atherosclerosis is still controversial, with many researchers supporting leptin's role as an atherogenic factor, while others studying its antiatherogenic properties." (PMID 26064110, 2015). "Leptin plays an important role in atherosclerosis by initiating leukocyte and macrophage recruitment to the endothelial wall." (PMID 25573199, 2015). "Ultimately, a better understanding of the detailed mechanisms of leptin expression in hypoxic HCASMCs will provide us new insight in prevention and therapy for leptin-related atherosclerosis, a condition frequently encountered in patients suffering from CVDs." (PMID 25573199, 2015). "In this review, we will discuss the effect of leptin on the cardiac and vascular system, focusing on cardiac hypertrophy, angiogenesis, the vasoactive response, blood pressure, and atherosclerosis." (PMID 26064110, 2015). "Recent in vitro and in vivo studies have indicated that, in addition to its major roles in energy metabolism, leptin is also involved in the pathophysiology of atherosclerosis." (PMID 24410779, 2014). "Leptin is reported to play an important role in the early stages of atherosclerosis development by initiating leukocyte and macrophage recruitment to the endothelial wall." (PMID 25375161, 2014). "Some adipokines participate in the pathogenesis of atherosclerosis and are also mediators of inflammation; among these, leptin and adiponectin are highly relevant in RA." (PMID 25243145, 2014). "Leptin has effects on macrophage lipid accumulation that are of potential importance in atherosclerosis: macrophages treated with leptin form cytoplasmic lipid bodies and synthesize the inflammatory eicosanoid leukotriene B4." (PMID 23122912, 2013). "The same group also reported independent relationships between serum leptin and proinflammatory lipid concentrations as well as atherosclerosis in patients with lupus." (PMID 23690663, 2013). "The levels of adipokines (adiponectin, leptin, resistin, and TNF-α) in patients with PAOD caused by atherosclerosis were successfully investigated." (PMID 22547903, 2012). "Here, we present an updated review based on the function played by four adipose tissue-derived factors (leptin, adiponectin, visfatin, and resistin) in atherosclerosis and different rheumatic diseases." (PMID 22910888, 2012).
atherosclerosis (continued). "The aim of our study was to assess the serum levels of adipokines (adiponectin, leptin, resistin, and TNF-α) in patients with PAOD caused by atherosclerosis." (PMID 22547903, 2012). "Serum leptin levels have been reported to be elevated in RA patients and to correlate to accelerated atherosclerosis, thus potentially accounting for increased incidence of cardiovascular disease afflicting RA patients." (PMID 22866899, 2012). "The impact of leptin on atherosclerosis and neointimal hyperplasia has been confirmed in a few experimental animal models and numerous clinical studies." (PMID 23316287, 2012). "It has been found that the adipose tissue is connected with the pathogenesis of atherosclerosis as a result of a secretion of a multitude of pro- and antiatherogenic cytokines and adipokines such as adiponectin, leptin, resistin, and acute-phase proteins." (PMID 22547903, 2012). "Even so, other reports have suggested that leptin does contribute to atherosclerosis and CVD in obese subjects." (PMID 20847813, 2010). "Higher leptin levels correlated with elevated lipid concentration (cholesterol and triglycerides), left ventricular hypertrophy and lower clinical atherosclerosis score in a study involving peritoneal dialysis patients." (PMID 20066136, 2008). "The role of leptin in the pathogenesis of atherosclerosis also remains uncertain." (PMID 41594231, 2026). "Moreover, serum leptin levels were positively correlated with carotid intima-media thickness, suggesting a potential role of leptin in atherosclerosis." (PMID 40584532, 2025). "PVAT is a source of NO, adipocyte-derived factors, leptin, and adiponectin, which may play roles in reducing spasm, inhibiting atherosclerosis and thrombosis, and regulating of vascular tone." (PMID 40338976, 2025). "Therefore, the connection between leptin levels and atherosclerosis is complex, involving multiple cell types and molecular pathways, providing fresh insights for preventing and treating cardiovascular diseases (CVDs)." (PMID 40861271, 2025). "Leptin controls energy balance and appetite at physiological levels, but in mice with obesity and diabetes, its elevated levels lead to hyperleptinemia, which supports atherosclerosis development." (PMID 40861271, 2025). "In addition to ghrelin, the adipocyte-derived cytokines leptin and adiponectin have various effects on atherosclerosis progression." (PMID 40137085, 2025). "However, excess leptin in obese individuals enhances atherosclerosis by stimulating oxidative stress and cholesterol absorption." (PMID 39335642, 2024). "Research indicates that leptin may have a direct impact on endothelial cells, influencing vascular function and contributing to the development of atherosclerosis." (PMID 39202262, 2024). "Abnormal leptin signaling may lead to an inflammatory response and atherosclerosis, but the mechanism in which the altered leptin signaling impacts cardiac microvessel angiogenesis has not been fully understood." (PMID 39317805, 2024). "Leptin was included in this study due to its well-documented but controversial involvement in stroke and its potential role as a biomarker for inflammation and atherosclerosis." (PMID 39336454, 2024). "Additionally, leptin was found to act as a chemoattractant and migration promoter for monocytes and macrophages, further accelerating the progression of atherosclerosis." (PMID 39335642, 2024). "It was mentioned that atherosclerosis is an indirect effect of high leptin levels." (PMID 39062887, 2024). "Additionally, the study aims to investigate the relationship between leptin levels and subclinical markers of atherosclerosis, such as nitroglycerin-mediated vasodilation (NMD), flow-mediated vasodilation (FMD), and pulse wave velocity (PWV) in CKD." (PMID 39062887, 2024). "Leptin could serve as a prominent biomarker of atherosclerosis and inflammation in the early post-stroke period; however, further study is warranted with a larger sample size." (PMID 37342754, 2023).
atherosclerosis (continued). "Moreover, it has been demonstrated that leptin can reduce free radicals, oxidative stress, and atherosclerosis in OSAS patients." (PMID 37507968, 2023). "We chose adipokines like adiponectin, visfatin, leptin, resistin, chemerin, and vaspin to investigate the crucial adipokines that may play roles in atherosclerosis." (PMID 36158825, 2022). "It has also been noted that leptin promotes the calcification of cells derived from vascular tissue, which is also of great interest given the importance of vascular calcification in CVDs, particularly in atherosclerosis." (PMID 36499312, 2022). "Regarding thyroid hormones themselves, subclinical hypothyroidism may be associated with atherosclerosis, as TSH directly stimulates hepatic gluconeogenesis and cholesterol synthesis, and leptin secretion in adipocytes." (PMID 36584082, 2022). "Evidence has also been found that leptin induces the activation of proinflammatory signaling pathways and the increased synthesis of proinflammatory mediators, thereby resulting in vascular inflammation, endothelial dysfunction and atherosclerosis." (PMID 36467062, 2022). "Moreover, leptin induces the proliferation of vascular and endothelial cells, which also play an important role in atherosclerosis development." (PMID 34836100, 2021). "While these observations may imply a conflicting role of leptin and leptin signaling in the pathogenesis of atherosclerosis, it is conceivable that obese and diabetic patients develop a state of ‘selective’ leptin resistance." (PMID 34064112, 2021). "However, recent studies have shown that ApoE-/-/Thbs1 -/- mice treated with exogenous leptin display significant decreases in body weight and attenuation of atherosclerosis." (PMID 33854480, 2021). "Together, these results suggest a regulatory role of leptin in pathogenesis of atherosclerosis." (PMID 34064112, 2021). "With an increase in the degree of atherosclerosis, LEP expression increased." (PMID 33735200, 2021). "In addition to the pleiotropic effects that regulate metabolic, immune, and endocrine functions, leptin is undoubtedly involved in the pathogenesis of atherosclerosis, which is confirmed in both experimental and clinical studies." (PMID 33735200, 2021). "Some studies suggest that leptin’s induction of atherosclerosis is receptor-dependent." (PMID 34178553, 2021). "In this study, we found lower levels of plasma leptin in Gal12‒/‒ mice, suggesting that the ablation of galectin-12 may have a protective benefit against atherosclerosis." (PMID 32752134, 2020). "The inconsistent correlation of leptin levels with preclinical atherosclerosis may depend on the pathophysiological context of patients, medications, or other factors not yet identified." (PMID 33192583, 2020). "In addition, leptin can have a direct effect on endothelial and vascular smooth muscle cells and a high level of leptin is involved in the pathogenesis of atherosclerosis." (PMID 33148166, 2020). "Second, adipocytokines, i.e. fat-related inflammatory markers such as IL-6 and leptin, play an important role in atherosclerosis including initial activation of endothelial cells, through atherosclerotic progression and, ultimately, its final complication, thrombosis." (PMID 32933542, 2020). "To determine whether galectin-12 may be involved in the pathogenesis of atherosclerosis, we measured leptin concentration in the sera of galectin-12 wild type (Gal12+/+) and knockout (Gal12−/−) mice." (PMID 32752134, 2020). "EAT may promote atherosclerosis through paracrine and endocrine pathways exerted via the secretion of adipocytokines such as adiponectin and leptin." (PMID 32024124, 2020). "Indeed, while leptin deficiency has been shown to protect apolipoprotein-E-deficient mice fed an atherogenic diet from the development of atherosclerosis lesions, exogenous leptin significantly increases atherosclerotic areas in apoE-deficient mice." (PMID 31656583, 2019).
atherosclerosis (continued). "Moreover, the perivascular adipose tissue (PVAT) appears to be crucial as a source of proinflammatory cytokines and as a site of interaction for leptin contributing to endothelium dysfunction and atherosclerosis progression." (PMID 31780867, 2019). "Leptin plays a role in stimulating vascular inflammation, vascular smooth muscle hypertrophy, and augmenting blood pressure, which contributes to the pathogenesis of atherosclerosis and leads to arterial stiffness." (PMID 29304064, 2018). "While adiponectin may be protective in atherosclerosis by diminishing endothelial injury, which is the first step in atheroma formation, leptin increase the secretion of inflammatory markers." (PMID 28068986, 2017). "However, elevated blood levels of leptin are known to be closely associated with the development of IR, which is not only a sign of T2DM, but also a metabolic risk factor of atherosclerosis and MI." (PMID 26989445, 2016). "Recently, studies in vitro and in vivo have suggested that leptin could also be involved in the pathophysiology of atherosclerosis." (PMID 27663646, 2016). "This study proposed that leptin treatment could improve dyslipidemia and thus attenuate atherosclerosis in cases of type 1 diabetes." (PMID 26064110, 2015). "The present study suggests that at elevated levels, leptin may favor atherosclerosis by promoting the synthesis of TNF-α and insulin." (PMID 25762868, 2015). "In a study that involved Ins2+/Akita:apoE−/− mice which developed type 1 diabetes, hypercholesteremia, and atherosclerosis spontaneously, severe leptin deficiency was seen compared to nondiabetic Ins2+/+:apoE−/− mice." (PMID 26064110, 2015). "Paradoxically, some researchers believe that leptin reduces atherosclerosis." (PMID 26064110, 2015). "Several studies have shown an independent relationship between high leptin levels and atherosclerosis, myocardial infarction, stroke, and coronary artery intimal hyperplasia, suggesting that leptin may increase risks of CVDs." (PMID 25573199, 2015). "Leptin has been documented to influence a multitude of organ systems, that is, central nervous system (appetite regulation, satiety factor) and cardiovascular system (endothelial dysfunction leading to atherosclerosis)." (PMID 25650072, 2015). "Leptin was originally identified as a regulator of food intake and energy expenditure, but it also increases blood pressure and promotes the development of atherosclerosis." (PMID 25303952, 2014). "We can speculate that the relatively low leptin concentration in OW/O Tepehuán could protect them against the development of atherosclerosis." (PMID 24825928, 2014). "Leptin inhibition would not be expected to influence either leptin-mediated metabolic risk or atherosclerosis in RA." (PMID 23690663, 2013). "Our findings indicate the involvement of FABP4 and leptin in the progression of atherosclerosis and plaque rupture, and suggest that down-regulation of PPAR/adipocytokine signaling within plaques may have therapeutic potential." (PMID 23122912, 2013). "Therefore, the in vivo efficacy of the compound to protect against atherosclerosis was first examined in double LDL-R and leptin deficient mice (DKO)." (PMID 22662181, 2012). "Leptin is a nonglycosylated peptide hormone, encoded by the gene LEP, with proinflammatory activities, and higher serum levels both in RA and atherosclerosis." (PMID 22927710, 2012). "In another study, leptin signaling directly promoted atherosclerosis and may therefore represent a therapeutic target for the prevention of atherosclerosis." (PMID 17617917, 2007). "An Iranian study aimed at determining a potential relationship between psoriasis with subclinical atherosclerosis, where psoriatic patients, in contrast to controls, demonstrated increased carotid intima-media thickness, which was accompanied by increased serum levels of resistin and leptin." (PMID 40095687, 2025).
atherosclerosis (continued). "Specifically, it highlights the strong correlation of leptin with ATM and testosterone in pre-dialysis and dialysis patients, the gender variation in leptin in CKD, and the association of leptin with vascular smooth muscle dysfunction as an atherosclerosis marker in women undergoing chronic HD." (PMID 39062887, 2024). "Leptin, adiponectin, interleukin-6, and tumor necrosis factor are only a few cytokines and bioactive mediators released by adipose tissue, an active endocrine and paracrine organ that may affect blood flow and encourage atherosclerosis." (PMID 37168312, 2023). "Changes in the expression of leptin and LEPR due to genetic and environmental factors may lead to dysfunction of the leptin system, disturbances in energy balance, weight gain, and risk for developing T2DM or atherosclerosis." (PMID 36984867, 2023). "Additionally, leptin and adiponectin produced by adipose tissue may protect against atherosclerosis and improve the ischemic state of the myocardium." (PMID 37805494, 2023). "For example leptin, which is secreted from adipose cells, has been shown to affect cardiovascular homeostasis and stimulate both vascular inflammation and smooth muscle hypertrophy, all of which may contribute to atherosclerosis and coronary heart disease." (PMID 35101102, 2022). "Leptin and adiponectin (APN) mediate proatherogenic and antiatherogenic responses, respectively, and hence, determining the plasma or serum levels of leptin and adiponectin alone or in combination may act as a novel prognostic biomarker for inflammation and atherosclerosis in stroke." (PMID 34685473, 2021). "In addition, adiponectin and leptin are both co-related towards the progression of atherosclerosis." (PMID 33562069, 2021). "The observed discrepancy in the beneficial vs. detrimental effects of leptin on development and progression of atherosclerosis may be due to differences in leptin concentration (physiological vs. supra-physiological) and animal models (lean vs. obese phenotype) utilized in various studies." (PMID 34064112, 2021). "Moreover, ob/ob mice (with leptin gene knockout) are resistant to atherosclerosis." (PMID 31780867, 2019). "Additionally, the significance of AMPK in vascular function is well-supported by anti-atherosclerosis agents, including statins, thiazolidinediones, leptin and rosiglitazone, which exhibit anti-atherosclerosis effects, at least partially, through the activation of AMPK." (PMID 31143119, 2019). "Moreover, recent studies showed that leptin affects the development of atherosclerosis." (PMID 28950870, 2017). "Elevated levels of total cholesterol, PLTP, RANTES, IL-6, insulin and leptin, which showed correlation with 18F-FMCH uptake, have been linked with increased atherosclerosis thus lending support to the association between 18F-FMCH uptake and the risk of atherosclerosis." (PMID 26852231, 2016). "Because defective leptin signaling was found to modulate inflammation and atherosclerosis, we also studied the relation between low adiponectin (Adipoq) and Irak3 expression in aortic extracts of high-fat and insulin resistant LDL-receptor deficient mice characterized by high plasma leptin levels." (PMID 23620818, 2013). "Neither leptin nor adiponectin concentrations were associated with atherosclerosis." (PMID 23690663, 2013). "In addition, in light of numerous clinical data suggesting a causative linkage between inflammation and enhanced atherosclerosis, we further hypothesized that tumor necrosis factor (TNF)-α might be involved in leptin induction within the carotid plaque." (PMID 23316287, 2012). "Indeed, using a lupus animal model, it was determined that leptin enhanced the proinflammatory high-density lipoproteins scores and atherosclerosis induced by a high-fat diet, indicating that factors related with metabolic syndrome can accelerate the disease and its cardiovascular complications." (PMID 22910888, 2012).